PTH (parathyroid hormone)
Diseases named in the same sentence as PTH in open-access papers (continued):
Sharing a sentence is not in itself a finding about the gene and the disease.
nephrocalcinosis (continued). "In the present study, higher serum PTH, 1.25(OH)2D, and urinary calcium were found in patients with renal calcifications compared to those without calcifications, and these parameters can be predictors of urolithiasis/nephrocalcinosis." (PMID 35437440, 2022). "Additionally, our experience further supports the notion that nephrocalcinosis can occur even on standard doses of calcitriol and oral calcium, and normal level of serum calcium, phosphorus, PTH and 25-(OH)D3." (PMID 33004071, 2020). "Additionally, this study corroborates that nephrocalcinosis can occur even on standard doses of calcitriol and oral calcium, and normal level of serum calcium, phosphorus, PTH and 25-(OH)D3." (PMID 33004071, 2020). "Furthermore, no serious adverse events (AEs), deaths, remarkable increase or decrease in the corrected calcium or intact PTH levels, or signs of nephrocalcinosis or its worsening were observed after treatment." (PMID 30828689, 2019). "Treatment of nephrocalcinosis with cinacalcet is safe and may improve this condition by increasing serum phosphate and reducing serum calcium and intact parathyroid hormone." (PMID 28390426, 2017). "A six-month-old male with Sanjad-Sakati syndrome, confirmed by genetic mutation in TBCE (tubulin-specific chaperone E) gene, had HPT (PTH <0.6 pmol/L) and was stable on standard doses of ACD, though had already developed signs of nephrocalcinosis." (PMID 28993435, 2017). "We recently reported that the peri-procedural use of recombinant PTH in APECED patients was safe and successfully maintained serum calcium levels without the need for intravenous calcium supplementation that can worsen nephrocalcinosis." (PMID 34790633, 2021). "Novel therapies such as recombinant PTH could maintain serum calcium levels without requiring intravenous calcium injection, which may exacerbate nephrocalcinosis." (PMID 40000975, 2025). "Unfortunately, data on FGF23, PTH, and urinary electrolytes were not available in our study; and hence, their involvement in nephrocalcinosis could not be investigated." (PMID 35043997, 2022). "Additionally, this study measured for nephrocalcinosis, hypercalcemia, serum immature parathyroid hormone, and creatinine in both IV and SC groups and found no increases." (PMID 34203792, 2021). "There were no recorded increases of nephrocalcinosis, serum parathyroid hormone, or creatinine." (PMID 34203792, 2021).
calcification (66 papers, 2010 to 2025). Process by which organic tissue becomes hardened by the physiologic deposit of calcium salts. "Other biomarkers associated with CKD–MBD, including calcium, phosphate, and PTH, have been linked to vascular calcification and cardiovascular mortality." (PMID 40283096, 2025). "Vascular calcification, linked to bone mineral metabolism disorders such as elevated serum phosphate, parathyroid hormone (PTH), and FGF23, well-known uremic toxins, aggravate this risk." (PMID 40559875, 2025). "Vascular calcification remains a key contributor to cardiovascular disease in this population and is strongly associated with elevated PTH levels." (PMID 40362848, 2025). "Given that phosphorus concentrations drive other disorders associated with increased CV risk (e.g., endothelial dysfunction, vascular calcification, fibroblast growth factor-23, parathyroid hormone), phosphate is a logical target to improve CV health." (PMID 35497793, 2022). "It has been reported that high serum phosphate and PTH distinctly regulate bone loss and vascular calcification in experimental CKD rats." (PMID 35172689, 2022). "1-α-hydroxy vitamin D (calcitriol) was associated with greater vascular calcification than paricalcitol, even though there was equivalent suppression of PTH in these animal models." (PMID 24066946, 2013). "In addition, mineral metabolism disorders, including disturbances in calcium, phosphate, and parathyroid hormone (PTH) levels, play a pivotal role in vascular calcification, a hallmark of cardiovascular disease in CKD patients." (PMID 39595570, 2024). "Assessment of parameters known to influence vascular calcification, e.g. phosphate, calcium and serum levels of parathyroid hormone as risk factors for ESKD could also be relevant, but were unavailable in this study." (PMID 33713332, 2021). "Here, high ALP activity belonged to the syndrome of MBD because high plasma ALP activity matched elevated bone ALP isoforms, was associated with high levels of osteocalcin and PTH, as already described, and with the presence of arterial calcifications, in line with the literature." (PMID 33425894, 2020). "Given that the association with PTH and vascular calcification, the possibility would raise that the PTH management may have an impact on the total number of the outcome." (PMID 31856757, 2019). "Moreover, ALP levels are associated with calcium-phosphate and PTH abnormalities and so vascular calcification and heart failure may represent pathogenetic links." (PMID 38913269, 2024). "These calcifications may arise due to the treatment of hypoPT with high doses of calcium and vitamin D. Furthermore, with low levels of PTH, the phosphate levels may increase and cause an increased calcium–phosphate product which over time leads to calcifications." (PMID 37487033, 2023). "MBD is a triad of biochemical abnormalities (calcium, phosphate, parathyroid hormone (PTH) and 1,25-dihydroxyvitamin D), bone abnormalities (short stature, reduced mineralization, and increased risk of fractures), and extra-skeletal calcification." (PMID 37997994, 2023). "MBD is the triad of biochemical abnormalities (of calcium, phosphate, parathyroid hormone (PTH) and 1,25-dihydroxyvitamin D), bone abnormalities (short stature, reduced mineralisation and increased risk of fractures) and extra-skeletal calcification." (PMID 31240395, 2020). "Controlling abnormalities in serum levels of phosphorus, calcium, vitamin D, and parathyroid hormone has been recommended to prevent the progression of vascular calcification and cardiovascular morbidity and mortality in patients with CKD." (PMID 31261703, 2019). "In particular, the therapy did not adversely affect the calcium, phosphorus, or parathyroid hormone (PTH) levels or promote vascular calcification." (PMID 31035488, 2019).
calcification (continued). "A novel aspect of this study was the comprehensive assessment of the association of arterial calcification with bone mineral markers including FGF23, sKl, phosphate and PTH." (PMID 28870151, 2017). "The balance between stimulation and inhibition of calcification is disturbed in renal disease, and the final action of i-PTH is ectopic vascular calcification." (PMID 28933414, 2016). "The increment of calcifications after one year was predicted by Age, serum Calcium, PTH and Fetuin-A." (PMID 20565936, 2010). "A prospective clinical study demonstrated that in HD patients with baseline parathyroid hormone levels up to 300 pg/mL, reducing the calcium concentration in the dialysate could slow coronary calcification progression and improve bone metabolism." (PMID 40755245, 2025). "Pharmacological intervention upon the RAS axis is advisable since both spironolactone and Angiotensin-converting enzyme inhibitors proved consistent reduction in PTH and calcium levels, thereby diminishing the toxic potential of elevated PTH and delaying surgical treatment of valvular calcification." (PMID 38785509, 2024). "Some evidence suggests that a relationship exists between adynamic bone disease or very low serum PTH levels and high mortality, but the interpretation of this information is biased by many other factors, such as vascular calcification, fractures, and hormonal changes 28,29." (PMID 32756862, 2020). "Noteworthy, CKD patients with low and stable PTH levels may have Adynamic Bone Disease (ABD), that is associated with higher CV risk possibly dependent on increased vascular calcifications." (PMID 30138402, 2018). "This phenomenon may be attributed to the irreversible loss of renal function, CKD exacerbation, elevated serum IS concentrations, decreased Klotho protein levels, and disturbances in calcium, phosphorus, and PTH, ultimately culminating in vascular calcification." (PMID 38385060, 2024). "In addition, AIF-1 could mediate elevations in serum phosphorus, FGF23, PTH, and vascular CCR2 as demonstrated in the present study, which was previously thought to be pathways of NF-κB causing vascular calcification." (PMID 35937793, 2022). "A higher serum level of i-PTH is a consequence of more severe renal hyperparathyroidism, and may increase the intensity of peritoneal calcification in long-term PD patients who have been exposed to hypertonic dialysate, repeated peritonitis, or excessive vitamin D therapy." (PMID 29293548, 2018). "Mineral and bone disorder may contribute to accelerated vascular calcification, and its markers (increased serum phosphate, calcium, parathyroid hormone [PTH], and fibroblast growth factor 23 concentration) have all been independently associated with increased mortality in dialysis patients." (PMID 25040468, 2015). "Age and HD vintage, PTH and CRP are significant factors of coronary calcifications on the bivariate analysis while regression analysis selected Age and HD age." (PMID 20565936, 2010). "In patients undergoing dialysis, chronic inflammation and disturbances in mineral metabolism, particularly involving calcium, phosphorus, and parathyroid hormone (PTH), accelerate vascular and valvular calcification, resulting in a higher prevalence of AS than in the general population." (PMID 41020020, 2025). "Therapy with inhibitors of the RAS axis reduces PTH levels in the human population, while the lack of this medication correlated with a more rapid progress in valvular calcification during the Japanese Aortic Stenosis Study." (PMID 38785509, 2024). "Furthermore, a lack of PTH reduces renal excretion of phosphate, causing hyperphosphatemia, and consequently an increased calcium-phosphorus product, which could cause vascular calcification and increase the cardiovascular risk." (PMID 38578437, 2024).
calcification (continued). "It is characterized by low serum calcium levels associated with insufficient PTH levels, changes in the phosphate/PTH balance that can lead to vascular calcification, damage to accompanying or nonaccompanying reactions, and increased neuromuscular excitability and soft tissue calcification." (PMID 40713713, 2025). "Well-controlled serum levels of phosphorus and PTH through comprehensive management might delay the progression of CKD, prevent the occurrence and progression of vascular calcification and cardiovascular events, and reduce the occurrence of anxiety and depression in patients with CKD." (PMID 37046867, 2023).
mineral bone disorder (66 papers, 2016 to 2026). "Third, serum 1,25(OH)2D is closely linked to kidney function and parameters of CKD–mineral bone disorder, including phosphate and PTH." (PMID 41597410, 2026). "Bone mineral disorder markers (plasma calcium and PTH) were also controlled adequately to maintain in target." (PMID 36835894, 2023). "Plasma phosphate and PTH concentrations remained relatively stable during the 24-month follow-up period, indicating that divalent ions and bone mineral disorders were adequately controlled." (PMID 36835894, 2023). "Mg is an important factor in CKD mineral bone disorders (CKD-MBD) as it can suppress parathyroid hormone (PTH) secretion, activate the calcium-sensing receptor, promote osteoblast activity, and reduce intestinal phosphate absorption." (PMID 36771254, 2023). "In CKD-related mineral bone disorder, all the disturbances in calcium, phosphorus and PTH must be collectively considered when selecting the appropriate treatment." (PMID 29391567, 2018). "In the newly updated KDIGO guidelines on CKD-related mineral bone disorder it is suggested that patients requiring PTH-lowering therapy could be treated by calcimimetics, calcitriol, vitamin D analogues or any appropriate combination of these treatments." (PMID 29391567, 2018). "Mineral and bone disorder (CKD–MBD) contributes to calcification via disturbances in calcium–phosphate homeostasis and parathyroid hormone (PTH) signaling." (PMID 41470171, 2025). "Bone Mineral Disorders: HDF improves phosphate removal, lowering parathyroid hormone (PTH) and fibroblast growth factor (FGF23) levels." (PMID 40283444, 2025). "Both BUN and PTH are critical indicators of renal and mineral metabolic health, suggesting incorporating BUN-PTH dynamics into predictive models for mineral bone disorder progression in CKD will be valuable." (PMID 39484207, 2024). "In accordance with the 2017 KDIGO CKD-Mineral and Bone Disorder guideline, in patients with CKD-5D, a target PTH range of two to nine times the upper limit of normal is recommended." (PMID 35172689, 2022). "Alkaline phosphatase, indicative of bone turnover, had a median level of 88 UI/L (interquartile range: 66–124 UI/L), whereas serum parathyroid hormone (PTH) levels, crucial for understanding bone mineral disorders in ESKD, showed a median value of 243 pg/mL (interquartile range: 118–460 pg/mL)." (PMID 39595171, 2024). "CKD–mineral bone disorder (CKD-MBD), a systemic disorder resulting from CKD, is characterized by abnormalities in calcium, phosphorus, parathyroid hormone (PTH), and vitamin D metabolism, resulting in irregularities in bone histology, linear growth, and strength." (PMID 39062256, 2024). "Furthermore, impaired mineral ion metabolism leads to mineral bone disorder (MBD) in CKD, especially due to serum phosphorous, parathyroid hormone (PTH), Vitamin D, and calcium." (PMID 37835901, 2023). "These significant associations persisted after further adjustment for clinical factors related to malnutrition-inflammation-atherosclerosis (MIA) syndrome (serum albumin, CRP, and hemoglobin) (model 2) and mineral and bone disorders (MBD) (1,25-dihydroxyvitamin D3 and whole PTH) (model 3)." (PMID 27662624, 2016). "Serum PTH and calcium levels fluctuated over time, leading to discontinuation of cinacalcet 12 months postoperatively when PTH had dropped to 184 pg/mL, below the target values for dialysis (the normal upper limit is 2–9 according to CKD-Mineral Bone Disorder (CKD-MBD) guidelines)." (PMID 40149691, 2025). "Likewise, CKD mineral bone disorder activity as indicated by parathyroid hormone, serum calcium, and serum phosphorus levels did not associate with the likelihood of KRT initiation." (PMID 39291215, 2024).
end-stage renal disease (65 papers, 2008 to 2026). "The appearance of first-degree atrioventricular block and mitral annulus calcification in an end-stage renal failure patient with elevated parathyroid hormone levels should raise the suspicion of metastatic cardiac calcification." (PMID 33728211, 2021). "High levels of parathyroid hormone have been associated with left ventricular hypertrophy and high levels of NT-proBNP in patients with CKD and end-stage renal-disease." (PMID 25112372, 2014).
parathyroid tumors (64 papers, 2006 to 2026). "This alignment underscores the diagnostic relevance of elevated calcium and PTH levels in identifying parathyroid tumors among our patients." (PMID 39213924, 2024). "The overexpression of cyclin D1 in parathyroid neoplasms can be caused by pericentric inversion of chromosome 11p that results in CCND1 gene control by parathyroid hormone gene promoter." (PMID 35805976, 2022). "Considering these data on the association between PTH and miR-199b-5p in parathyroid tumors, it will be important to focus future studies on the role of miR-199b-5p in parathyroid tumorigenesis." (PMID 30104706, 2018). "We also observed significantly lower expression of miR-199b-5p in sporadic parathyroid tumors, and miR-199b-5p expression was negatively associated with PTH levels, indicating a specific role for this miRNA in parathyroid tumorigenesis." (PMID 30104706, 2018). "Parathyroid tumors are often associated with parathormone (PTH) hypersecretion determining primary hyperparathyroidism (PHPT), which represents the third most common endocrine disease following diabetes and thyreopathies." (PMID 28157158, 2017). "However, individuals with heterozygous MEN1 gene mutation often exhibit parathyroid tumors and have high parathyroid hormone (PTH) levels due to the fact of overproduction and secretion from the parathyroid cells of the parathyroid gland." (PMID 35892371, 2022). "Although its exact functions in parathyroid tumors are unknown, miR-199b-5p was found to be negatively correlated with serum PTH which associated with tumor size in sporadic parathyroid tumors in our study." (PMID 30104706, 2018). "Given the composition of the inflammatory infiltrates, the observed association to higher PTH levels could be explained either by direct interaction between immune cells and parathyroid cells, changes in the local cytokine milieu affecting parathyroid tumor cells or an unknown confounding factor." (PMID 28855268, 2017). "For instance, suppose a patient with a preoperative intact PTH value of 800 pg/mL whose ultrasonography suggests a parathyroid tumor with a volume of 500 mm3 log-transformed to 6.21." (PMID 38525667, 2025). "A positive correlation was identified between parathyroid tumor volume and both preoperative intact parathyroid hormone (PTH) (Spearman's r = 0.503) and calcium values (Spearman's r = 0.338)." (PMID 38525667, 2025). "The results showed that parathyroid tumor volume was moderately correlated with preoperative serum intact PTH and calcium levels." (PMID 38525667, 2025). "Preoperative suspicion of a parathyroid tumor, despite normal PTH levels, led to omission of MIBI scintigraphy." (PMID 41476594, 2025). "In clarifying the relationship between preoperative biochemical data and parathyroid tumor volume, multiple regression analysis showed that parathyroid volume was significantly larger in males, with higher preoperative serum PTH and higher calcium levels." (PMID 38525667, 2025). "Preoperative serum intact PTH values correlate with tumor volume in functional parathyroid tumors, but the utility of intact PTH values appears limited for accurately predicting tumor size preoperatively." (PMID 38525667, 2025). "Men1 heterozygotic mice with parathyroid neoplasms were hypercalcaemic and hypophosphataemic, with inappropriately normal serum parathyroid hormone concentrations." (PMID 39409111, 2024). "Preoperative very high PTH or low vitamin D levels, impaired renal function, increased bone turnover and removal of large parathyroid tumors are predictive factors of increased postoperative PTH levels." (PMID 38622315, 2024). "The patient’s basal intact PTH was 96.2 pg/mL, which decreased to 93.3 pg/mL at 25 min and 72.4 pg/mL at 55 min after removal of the parathyroid tumor." (PMID 38662187, 2024). "Primary hyperparathyroidism (PHPT) is one of the most common endocrine disorder, and it is characterized by inappropriate secretion of PTH from parathyroid tumors and hypercalcemia." (PMID 37065733, 2023).